CAT (catalase)
Diseases named in the same sentence as CAT in open-access papers (continued):
Sharing a sentence is not in itself a finding about the gene and the disease.
sarcoidosis (8 papers, 2011 to 2025). Sarcoidosis is a multisystemic disorder of unknown cause characterized by the formation of immune granulomas in involved organs. "Recent studies by detecting Mycobacterium tuberculosis catalase–peroxidase have renewed interest in mycobacteria as a causative agent in sarcoidosis." (PMID 21484177, 2011). "In case of immunological sensitization for C. acnes, 3.5% of the sarcoidosis patients showed a positive ELISpot for C. acnes catalase." (PMID 36014067, 2022). "One possible mycobacterial antigen is Mycobacterium tuberculosis catalase–peroxidase (mKatG) because it has been more frequently identified in sarcoidosis tissues in comparison to healthy controls." (PMID 33036432, 2020). "Among our included studies, one study conducted by Song reported the detection of several M. tuberculosis antigens including catalase‐peroxidase antigen (mKatG) and Mtb 16S rRNA in nearly 40% of their sarcoidosis subjects as detected by in situ hybridization." (PMID 27479700, 2016). "Catalase and trigger factor are likely upregulated during intracellular proliferation of C. acnes and may serve as immunodominant antigens in sarcoidosis." (PMID 40837573, 2025). "Sarcoidosis patients exhibit elevated IFN-γ responses to catalase." (PMID 40837573, 2025). "Others have reported positive mycobacterial PCR in 26% of patients with sarcoidosis and suggest that residual mycobacterial catalase-peroxidase could be the tissue antigen triggering sarcoidosis." (PMID 35740604, 2022). "This difference in antigen stability may explain the immunohistochemical absence of catalase and trigger factor within granulomas despite strong T-cell responses to these antigens in sarcoidosis patients." (PMID 40837573, 2025). "Looking at the clinical phenotype, patients with a positive ELISpot for C. acnes catalase showed a trend towards more cutaneous involvement of the sarcoidosis and were significantly younger at diagnosis compared to patients without a positive C. acnes catalase ELISpot." (PMID 36014067, 2022). "Although models for granulomatous inflammation exist, e.g. Cutibacterium acnes, mycobacterial catalase–peroxidase and ESAT-6 models, leprosy, and schistosomiasis, it is probably not a model of the complex disease itself and certainly not of fibrotic sarcoidosis." (PMID 36543347, 2022).
adenoma (7 papers, 2013 to 2024). A neoplasm arising from the epithelium. "The results of the present study indicate that pistachios exhibit chemopreventive properties by inhibiting growth of adenoma cells, reducing levels of DNA damage and inducing CAT expression as well as apoptosis." (PMID 29258268, 2017). "Furthermore, the IgG response to HpaA was also positively associated with advanced adenoma development, while responses to HP0305, CagA and Catalase were associated with a higher risk for polyps." (PMID 39452767, 2024). "A genetic score comprising genes encoding for SOD2 (eight SNPs), CAT (11 SNPs) and GSTP1 (five SNPs), following an additive model of inheritance (0, 1 and 2 points awarded for every high-risk allele) or a SNP—adenoma risk-specific score, was explored for this purpose." (PMID 30987200, 2019).
bacteremia (7 papers, 2006 to 2021). "We report the draft genome sequence of Catabacter hongkongensis, a catalase-positive bacterium which causes bacteremia with high mortality." (PMID 25999561, 2015). "Bacteremia cannot be diagnosed based on clinical signs; it may be detectable if it occurs in connection with constant bacteriuria using a catalase-based calf-side urine test." (PMID 34438960, 2021). "The bacterium is facultative anaerobic, nonmotile, catalase-positive, and coagulase-negative and is known to cause catheter-related bacteremia and infective endocarditis." (PMID 27872773, 2016). "Gram-positive, catalase-negative, coccus-shaped organisms were isolated from all clinical samples of different organs suggesting bacteremia." (PMID 29950697, 2018). "Clinical laboratories should consider C. canimorsus in patients with bacterial sepsis and a recent history of a dog bite or animal exposure and with the laboratory observation of fastidious, oxidase- and catalase-positive, gram-negative rods with fusiform shape." (PMID 16494769, 2006).
diabetic cardiomyopathy (7 papers, 2013 to 2025). Diabetic cardiomyopathy is a disorder of the heart muscle in people with diabetes. "For example, chronic overexpression of catalase eliminated excessive ROS production in diabetic cardiomyocytes and protected against diabetic cardiomyopathy caused by oxidative damage." (PMID 24255720, 2013). "Our team and others have reported that overexpression of metallothionein, catalase, and manganese superoxide dismutase in the heart reverses diabetic cardiomyopathy in animal models of both T1DM and T2DM." (PMID 28272348, 2017). "Although recent findings demonstrate that catalase, autophagy and the nuclear factor κB (NF‐κB) signalling pathway are centrally involved in diabetic cardiomyopathy (DCM), the interplay between the three has not been fully characterized." (PMID 28643395, 2017).
diabetic neuropathy (7 papers, 2014 to 2025). A chronic, pathological complication associated with diabetes mellitus, where nerve damages are incurred due to diabetic microvascular injury involving small blood vessels that supply these nerves, resulting in peripheral and/or autonomic nerve dysfunction. "Malondialdehyde (MDA), superoxide dismutase (SOD), catalase (CAT), glutathione (GSH), glutathione peroxidase (GPX), and thiobarbituric acid reactive substances (TBARS) are the key biomarkers associated with diabetic neuropathy." (PMID 40434673, 2025). "Catalase impairment was also described in neuropathic conditions since decreased catalase efficiency was described in sciatic nerve of rats affected by diabetic neuropathy as well as in brain regions of animals with delayed neuropathy induced by organophosphate." (PMID 25036594, 2014).
gestational diabetes (7 papers, 2020 to 2025). Carbohydrate intolerance first diagnosed during pregnancy. "Crocetin decreased the expression levels of IL-6, TNF-α, and IL-1β, increased the levels of antioxidant enzymes such as SOD, GSH-Px, GSH, and CAT, and increased body weight in rats with STZ-induced gestational diabetes mellitus (GDM)." (PMID 38004168, 2023).
lung disease (7 papers, 2020 to 2023). "IgM autoantibodies targeting catalase could diminish the antioxidant potential in the airways and promote oxidative stress-mediated lung disease in CF." (PMID 37767091, 2023). "The 2-month treatment of the patients with lung disorder for a long time (27–30 years) exposing to SM with carvacrol (1.2 mg/kg) significantly enhanced the CAT and SOD activities, thiol level, and PEF values, but, declined the MDA level, total WBC and neutrophil count." (PMID 35662950, 2022). "Increasing airway catalase levels at the time of RSV infection could represent a potential novel therapeutic approach to ameliorate viral-induced lung disease." (PMID 31947722, 2020). "Our results suggest that increasing catalase expression/activity could exert a protective role in the context of RSV infection and represent a potential novel therapeutic target to ameliorate viral-induced lung disease." (PMID 31947722, 2020).
schistosomiasis (7 papers, 2016 to 2026). An infectious disease caused by parasitic trematodes of the genus Schistosoma that colonize human blood vessels and release eggs that can cause granulomatous reactions leading to acute (swimmer's itch or acute schistosomiasis syndrome) or chronic disease. "The antioxidant enzymes CAT and SOD were examined in order to evaluate how schistosomiasis causes oxidative damage in hepatic tissue." (PMID 36904204, 2023). "Our work confirmed the oxidative damage induced by schistosomiasis, which is indicated by significantly elevated serum levels of MDA and reduced CAT, SOD, and GSH-Px activities as well as TAC levels in S. mansoni-infected mice." (PMID 33996977, 2021). "Interestingly, oxidative stress due to schistosomiasis increased the level of MDA and reduced levels of SOD, CAT, and GSH-Px." (PMID 33996977, 2021). "However, since catalase activity was not directly assessed in our experimental model, further studies are needed to confirm this mechanism in the context of schistosomiasis." (PMID 41557748, 2026).
thyroid cancer (7 papers, 2009 to 2025). "Whereas the level of antioxidative defence increases in differentiated thyroid cancer, a decreased expression of mRNA encoding for CAT and SOD were found in anaplastic thyroid carcinoma, when compared to histopathologically unchanged thyroid tissue and to differentiated thyroid tumors." (PMID 23270549, 2012). "The ELISA assays revealed that IDET markedly reduced SOD and CAT activity in the supernatant of thyroid cancer cells, indicating its inhibitory effect on Nrf2 function." (PMID 41394539, 2025). "Studies have found that thyroid cancer patients had lower CAT levels, which may indicate that the patients' antioxidant defense mechanism is weak." (PMID 38449627, 2024). "Moreover, it has demonstrated that activities of SOD, CAT, and GPx were reduced in some types of thyroid cancer tissues." (PMID 35571253, 2022).
allergic asthma (6 papers, 2014 to 2021). A asthma with a basis in a pathological type I hypersensitivity reaction. "Antioxidant enzymes, such as GSH, catalase, and superoxide dismutase, offer protection from oxidation by suppressing the chronic inflammatory response and preventing the deterioration of lung tissue in allergic asthma." (PMID 28243240, 2017). "Moreover, the CAT −21A>T and GPX2 G>A gene polymorphisms had a strong antagonistic effect on the risk of allergic asthma in men." (PMID 24895604, 2014). "Oxidative stress is also a pathological manifestation of allergic asthma, the representative indexes of which are MDA, GSH-PX, SOD, and CAT." (PMID 33542675, 2021). "In addition, LOL treatment markedly enhanced Nrf-2/HO-1/NQO1 signaling with elevated the activities of anti-oxidant enzymes, such as GSH, CAT, and SOD, and suppressed the levels of ROS, NO, and TBARS in lung tissues of the OVA-challenged allergic asthma model." (PMID 32605045, 2020).
chronic myeloid leukemia (6 papers, 2014 to 2022). "This study shows that catalase activity is reduced in patients with decreased myeloid lineage cell; however, patients with leukocytosis from chronic myeloid leukemia had high catalase activity." (PMID 35600961, 2022). "According to some of the oldest research studies, in both acute and chronic myeloid leukemia there is a substantial increase in catalase activity when compared to normal cells." (PMID 33924068, 2021). "We demonstrate that sustained activation of STAT5 induced by Bcr-Abl in chronic myeloid leukemia (CML) cells promotes ROS production by repressing expression of two antioxidant enzymes, catalase and glutaredoxin-1(Glrx1)." (PMID 27566554, 2017).
chronic obstructive pulmonary disease (6 papers, 2014 to 2023). A chronic and progressive lung disorder characterized by the loss of elasticity of the bronchial tree and the air sacs, destruction of the air sacs wall, thickening of the bronchial wall, and mucous accumulation in the bronchial tree. "Both catalase and MnSOD are under the control of Forkhead box class O 3a (FoxO3), which significantly decreased in lungs of smokers and patients with chronic obstructive pulmonary disease, as well as in lungs of mice exposed to CS." (PMID 28105251, 2016). "Moreover, our study is in accordance with others showing elevated levels of lipid peroxidation products, such as MDA, and decreased levels of antioxidants, such as glutathione peroxidase and catalase, in patients with chronic obstructive pulmonary disease versus controls." (PMID 31878925, 2019).
Constipation (6 papers, 2019 to 2024). Infrequent or difficult evacuation of feces. "Together, SOD and CAT form an antioxidant chain that mitigates intestinal damage caused by constipation." (PMID 39857348, 2024). "Furthermore, constipation has been associated with the downregulation of cuprous zinc superoxide dismutase, manganese superoxide dismutase, and catalase, along with the upregulation of nitric oxide synthase and its product NO." (PMID 39014407, 2024). "During constipation, the production of ROS was significantly increased, and the activity and expression levels of SOD and catalase were decreased." (PMID 39857371, 2024). "In the present study, the serum levels of SOD, CAT and GSH-Px of both the aging rats and the constipation rats significantly decreased as compared to control rats, while the level of MDA increased." (PMID 33428599, 2021). "As compared to the control rats, the levels of SOD, CAT and GSH-Px significantly decreased in the aging rats and the constipation rats, while the activity of MDA increased." (PMID 33428599, 2021). "Further, LP‐CQPC01‐FSM increased the mRNA and protein expression of Cu/Zn‐SOD, Mn‐SOD, CAT, c‐Kit, SCF, and GDNF and reduced the expression of TRPV1 and NOS relative to those of the mice with untreated constipation." (PMID 31289655, 2019).
cystic fibrosis (6 papers, 2015 to 2025). Autosomal recessive disorder caused by pathogenic variants in the CFTR gene (cystic fibrosis transmembrane conductance regulator), which encodes a chloride and bicarbonate channel expressed in epithelial cells, and follow the diagnosis criteria. "Bordetella hinzii belongs to the Bordetella genus, which was reported as a Gram-negative and short rod-shaped bacterium with positive oxidase and catalase isolated from both humans and mice suffering from cystic fibrosis." (PMID 36874359, 2022). "However, heme-auxotrophic SCVs cannot generate functional catalase and SCVs isolated from the lungs of patients with cystic fibrosis have been reported to have reduced catalase activity." (PMID 25690100, 2015).
endometrial cancer (6 papers, 2009 to 2024). Primary or metastatic malignant neoplasm involving the endometrium (mucous membrane that lines the endometrial cavity). "Catalase activities of endometrial carcinoma cases were higher than those of the control cases (p = 0.027)." (PMID 34568983, 2021). "Additionally, N-acetylcysteine and catalase reduce levels of reactive oxygen species (ROS) and exhibit a beneficial impact on autophagy in endometrial cancer." (PMID 38543097, 2024). "Nevertheless, the elevation in catalase activity in endometrial carcinoma may be one of the adaptive mechanisms exerted by the host body against excessive produced reactive species by the tumor cells." (PMID 34568983, 2021). "Similarly, livin/BIRC7 expression and MDA were significant (p < 0.001), AUC = 0.998 and 0.991 respectively compared to 0.613 for catalase (p = 0.13) in predicting endometrial carcinoma." (PMID 34568983, 2021). "The ROC curve analysis was applied to assess the power of livin/BIRC7 expression, catalase activity, and MDA levels in discriminating between endometrial carcinoma, hyperplasia, and normal endometria." (PMID 34568983, 2021). "In differentiating endometrial carcinoma from endometrial hyperplasia, livin/BIRC7 expression was the most powerful with AUC = 0.94 compared to 0.87 and 0.59 for MDA and catalase respectively." (PMID 34568983, 2021). "In the current study, using ROC curve analysis, we found that livin/BIRC7 expression and MDA level but not the catalase could be used as additional dependable parameters in the diagnosis of the suspected cases with endometrial carcinoma and endometrial hyperplasia." (PMID 34568983, 2021).
endotoxemia (6 papers, 2020 to 2025). "Our results align with a previous studies showing that LPS-induced catalase depletion exacerbates kidney injury in a mouse model of endotoxemia." (PMID 40271532, 2025). "The application of resveratrol in endotoxemia rats can reduce the occurrence of oxidative damage by inhibiting erythrocyte lipid peroxidation and catalase (CAT) activity, reducing nitric oxide (NO) release, downregulating malondialdehyde (MDA) levels, and maintaining iron homeostasis." (PMID 35222035, 2022). "The activity of CAT and SOD, as well as the level of GSH, were found to be decreased in LPS-induced endotoxemia, aligning with the results of several previous studies." (PMID 38578526, 2025). "In a murine model of acute lung injury induced by LPS-induced endotoxemia, the H2S donor GYY 4137 attenuated the LPS-induced decrease in the antioxidative biomarkers catalase and SOD and the total antioxidant capacity (T-AOC)." (PMID 35628328, 2022). "Notably, both UDCA and CDCA significantly elevated the activity of CAT and GSH levels, thus increasing their antioxidative effects in the context of endotoxemia." (PMID 38578526, 2025). "Resveratrol treatment significantly inhibited iNOS expression, NO production, and peroxynitrite formation induced by endotoxemia and reduced LPS-induced adrenal oxidative stress, as evidenced by a decrease in MDA and an increase in various antioxidant biomarkers (T-AOC, CAT, and SOD activity)." (PMID 35222035, 2022).
fibrosarcoma (6 papers, 2020 to 2025). A malignant mesenchymal fibroblastic neoplasm affecting the soft tissue and bone. "The relative mRNA expression levels of selenoprotein W (SELENOW), SEPP1, masculoaponeurotic fibrosarcoma K (MafK), CAT, SOD1, SOD2, and NAD (P)H: quinone oxidoreductase 1 (NQO1) genes in TN + SeNPs-AOS group were higher than TN group (p < 0.05)." (PMID 38001826, 2023). "In response to stress, Nrf2 binds to the ARE present in gene promoters, with the small musculoaponeurotic fibrosarcoma (sMaf) as a partner, and induces antioxidant enzymes, such as HO-1, GPX, CAT, and NQO-1." (PMID 32916869, 2020). "Keap1: Kelch-like ECH-associated protein 1; Nrf2: Nuclear factor erythroid 2 p45 (NF-E2)-related factor; sMaf: Small musculoaponeurotic fibrosarcoma protein; ARE: Antioxidant response element; GSH: glutathione; SOD: superoxide dismutase; CAT: Catalase; GPx: Glutathione peroxidase." (PMID 33050575, 2020).
influenza (6 papers, 2012 to 2022). An acute viral infection of the respiratory tract, occurring in isolated cases, in epidemics, or in pandemics; it is caused by serologically different strains of viruses (influenzaviruses) designated A, B, and C, has a 3-day incubation period, and usually lasts for 3 to 10 days. "With the HFBI film, we determined the high-resolution cryo-EM structures of catalase and influenza HA trimer, both of which had a severe preferential orientation problem using the conventional cryo-vitrification protocol." (PMID 34907237, 2021).
kidney (6 papers, 2005 to 2023). "It is certain that an altered prooxidant–antioxidant balance, despite the higher activity of catalase, may lead to increased oxidative damage, and consequently play an important role in prostate carcinogenesis." (PMID 32899343, 2020). "In I/R induced kidney injury, to understand the involvement of ELF4 and whether this influences were related to OS and ERS, we assessed the change of OS index (SOD, CAT, and GSH-PX), OS related proteins (Nrf2, HO-1, and NQO-1), and ERS related proteins (GRP78, CHOP, and caspase-12)." (PMID 37474923, 2023).